NOTCH1 (notch receptor 1)
Diseases named in the same sentence as NOTCH1 in open-access papers (continued):
Sharing a sentence is not in itself a finding about the gene and the disease.
cancer (continued). "Knocking out GNA14 in cells can significantly promote cancer growth, and the related mechanism is linked to the activation of signaling pathways such as MAPK/JNK, PI3K/AKT, and Notch1." (PMID 37405532, 2024). "c-Myc, Cyclin E, c-Jun, Notch1, and mTOR are among the oncogenic proteins that specifically facilitate ubiquitination and proteasomal destruction, making them moniker cancer suppressors." (PMID 39528487, 2024). "It was also noticed that cyclin-D1, Notch-1, and Hes-1 were downregulated after luteolin treatment, demonstrating that luteolin prevented this cancer progression via suppressing Notch signaling." (PMID 38474604, 2024). "Jones and colleagues provide an example of how mutant NOTCH1 isoforms are commonly found in normal oesophageal tissue and can act as a preventive factor against cancer." (PMID 38172609, 2024). "In this study, we investigated the intricate interaction between ASPH and the Notch1 signaling pathway in various cancer cell lines." (PMID 38817852, 2024). "Notch1, a member of the Notch family, plays a critical role in the initiation and progression of human malignancies (Notch1 in Cancer Therapy, 2024)." (PMID 39749199, 2024). "Our experimental results have shown that TP has the potential to be an effective anticancer agent by inhibiting essential signals that are involved in cancer cell proliferation, such as Notch1 and STAT3 signaling." (PMID 38731894, 2024). "The therapeutic value of co-targeting ERK1 and Notch1 has yet to be demonstrated for RA but was shown effective in cancer in which Notch1 targeting enhanced ERK1 inhibitors’ efficacy in cancer patients." (PMID 39329767, 2024). "The mean percentage of NOTCH1-positive cells was highest in benign tumors (47.7%) and lowest in malignant tumors (18.8%), with precancerous lesions showing intermediate levels (41.2%)." (PMID 39063983, 2024). "The Notch1 signaling pathway is a crucial molecular system in regulating numerous cellular processes in various types of cancer." (PMID 40034926, 2024). "This study highlights the complex nature of ASPH-mediated regulation, involving not only the Notch1 pathway but also diverse pathways in different cancer types, and emphasizes the importance of targeting multiple pathways to reduce cancer progression." (PMID 38817852, 2024). "Next, we further explored the expression of the cancer stem cell markers Notch1, Nestin, and CD133 in GBM." (PMID 38473403, 2024). "To better demonstrate the function of USP11 in regulating NOTCH1 signaling, we utilized biochemistry and molecular assays coupled with bioinformatic analysis of cancer datasets to reveal a novel positive feedback loop between NOTCH1 and USP11 in T-ALL." (PMID 38007584, 2024). "NIFK-AS1 attenuated M2 polarisation in endometrial cancer-associated macrophages by sponging miR-146a, resulting in upregulation of Notch1 signalling and exosomal lncRNA RPPH1 in colorectal cancer promoted M2 polarisation, causing metastasis of cancer cells." (PMID 40176927, 2024). "The mean percentage of NOTCH1-positive expression was 18.8% (standard deviation (SD) = 40.3%) in normal histology, 41.2% (SD = 50.7%) in malignant tumors, 44.6% (SD = 49.8%) in precancerous tumors, and 47.7% (SD = 50.2%) in benign tumors." (PMID 39063983, 2024). "The effects of ASPH inhibitors on Notch1 pathway activity, cyclin D1 expression, and nuclear morphology contribute to the understanding of the multifaceted effects of these inhibitors on cancer cell behavior." (PMID 38817852, 2024). "We identified a total of 10 targets, including five targets with 15 known FDA-approved drug interactions with potential for therapeutic use or testing in Notch1-dependent cancers." (PMID 38043798, 2024).
cancer (continued). "Given its role in cancer and its therapeutic applications in a variety of disorders, it is valuable to identify the protein components of the NOTCH1 transcription complex and its functional protein-protein association network." (PMID 38043798, 2024). "A survey of the COSMIC chromosomal breakpoint dataset revealed that the NOTCH1 hotspot is a site of recurrent translocation in cancer (chr1:26,282,333, structural ID: COST195256)." (PMID 39341500, 2024). "Notch1 is tightly connected to other oncogenic signaling pathways and impacts proliferation, apoptosis, chemosensitivity, immune response, and cancer stem cells." (PMID 39456548, 2024). "Our research suggests that TP can hinder the growth of cancer cells by inhibiting the signaling pathways of Notch1 and STAT3." (PMID 38731894, 2024). "HES4 is a canonical target gene of Notch1 that plays an important role in normal breast epithelial differentiation and cancer development." (PMID 39545637, 2024). "For this reason, many studies have been going on to investigate the role of Notch1 signaling in different types of cancer." (PMID 40034926, 2024). "Notch 1 reportedly is correlated positively with matrix metal proteases in a variety of cancer types." (PMID 38585261, 2024). "E2F and neurogenic locus notch homolog protein 1 (Notch1) transcription factors induce Pin1 expression and are known to play an important role in cancer progression by regulating S-phase entry and differentiation, respectively." (PMID 38745861, 2024). "Epigallocatechin-3-gallate (EGCG), the main polyphenol in green tea, decreased the expression of Notch receptors including Notch1 and Notch2 in several cancer models." (PMID 39092224, 2024). "We first analyzed the pediatric cancer genome project (PeCan) database to determine the correlation between the 52 USPs and NOTCH1 at the mRNA level." (PMID 38007584, 2024). "ASPH is upregulated in various cancer types, where it promotes cancer progression mainly by regulating the Notch1 and SRC pathways." (PMID 38817852, 2024). "We find low levels of 3-HB in the plasma of leukemic mice compared to NLM (while in NOTCH1 T tumors it seems to accumulate, p = 0.07), similarly to another recent study, suggesting increased uptake/utilization of ketone bodies in cancer." (PMID 38928249, 2024). "For example, IL-6-induces Notch1 activation and cancer stem cell proliferation by the assembly of γ-secretase at membrane caveolae." (PMID 38612718, 2024). "Recently, it has been reported that NOTCH1 maintained a cancer stem cell–like phenotype in diffuse type GC by upregulation of a stem cell marker CD133." (PMID 37460910, 2023). "The significantly enriched biological processes included diseases of immune system, drug metabolism-cytochrome P450, PPAR signalling pathway, NOTCH1 signalling in cancer and the TGF-βsignalling pathway." (PMID 37142983, 2023). "In this review, we provide a detailed overview of the specific role of lncRNAs in the modulation of Notch1 signalling, from expression to activity, and their connection with the development of health disorders, especially cancers." (PMID 37628760, 2023). "MDSCs interact with CTCs via jagged canonical Notch ligand 1 (JAG1) and neurogenic locus notch homolog protein 1 (Notch1) supporting the adhesion of the cancer cell to the endothelium and extravasation." (PMID 37296987, 2023). "The NOTCH1 signaling pathway has been investigated as a therapeutic target for the treatment of cancers and inflammatory disorders." (PMID 37190117, 2023).
cancer (continued). "Only a few research papers have specifically addressed the role of NOTCH1 activation in HNSCC, although the link between deregulation of NOTCH1 signaling and cancer in humans is clear." (PMID 37205904, 2023). "Most of these interactions have been described in stem cells and various diseases including cancer, where aberrant ncRNA levels result in the dysregulation of NOTCH1 signalling." (PMID 37628760, 2023). "In contrast to the induction of stemness in cancer cells, stemness marker Notch1 intracellular signaling in CAFs acts as a molecular switch to regulate melanoma cell plasticity." (PMID 37046676, 2023). "For example, Notch1 inhibition in combination with a chemotherapeutic drug reduced CSC self-renewal in HNSCC CSCs in vitro and in vivo, confirming Notch1 as an ideal target for cancer treatments." (PMID 37305676, 2023). "In the results of functional analysis, ERPI was associated with cellular components (such as keratin filaments and blood microparticles) and enriched signaling by Notch1 HD domain mutants in cancer and signaling by VEGF pathways." (PMID 36968596, 2023). "Another broad cellular mechanism that has been exploited to target NOTCH1 protein levels within cancer cells is the use of proteasome inhibitors, such as Bortezomib." (PMID 37760535, 2023). "When the demethylation reagent 5-AzadC is applied, the hypermethylation regulation of MEG3 by DNMT1 is significantly inhibited, and uninhibited MEG3 exerts its inhibitory effect on cancer through the inhibition of Notch1 signaling pathway." (PMID 37901333, 2023). "They suggested the neurogenic locus notch homolog protein 1 (NOTCH1) and von Willebrand factor (vWF) as early biomarkers of DOX cardiotoxicity to address the clinically significant question of identifying cancer patients at risk for cardiotoxicity." (PMID 37296716, 2023). "We observed that the key factors of Notch1 signaling pathway and cancer stemness-related proteins were downregulated when MSI2 is silenced and upregulated when it is overexpressed." (PMID 37149661, 2023). "The Notch1 gene is responsible for regulating cancer cell differentiation, proliferation and maintenance in many different kinds of cancers including PC." (PMID 36635659, 2023). "Intriguingly, As2O3 has been shown to inhibit cell growth and induce apoptosis through inactivation of the Notch1 signaling pathway in different types of cancer cells." (PMID 36768603, 2023). "A number of approaches to inhibit NOTCH1 have potential benefits in various clinical aspects of cancer." (PMID 37190117, 2023). "For instance, BRD4 was required for IL-6-stimulated and Notch1-induced cancer migration in a triple-negative breast cancer model, indicating that BRD4 linked microenvironment inflammation to cancer propagation." (PMID 36627707, 2023). "Here, we show using human and mouse cancer models that during precachexia, tumors overactivate Notch1 signaling in distant WAT endothelium." (PMID 37749321, 2023). "It is widely accepted that Notch1 plays a role in mediating drug resistance in multiple malignant tumors, and our previous study indeed demonstrated that Notch1 increased the resistance to cisplatin in TNBC cells." (PMID 37391408, 2023). "The impediment of the Notch signalling pathway through Notch 1 and its downstream components is postulated to be responsible for observed anti-cancer attributes of current chemo-herbal combinations." (PMID 36685076, 2023). "Initial studies indicated that NOTCH1 alterations have a cytotoxic effect in protracted hematologic malignancies and T-cell acute lymphoblastic leukemia." (PMID 37205904, 2023). "Dysregulation of the Notch1 pathway has been frequently identified in different aggressive human cancers and has been shown to play an important role in cancer development." (PMID 35186194, 2022).
cancer (continued). "These Notch1-positive T-cells were surrounding cancer cells, possibly establishing immunological synapses for cancer cell killing." (PMID 36090975, 2022). "In vitro experiments additionally showed a reduction of migration and proliferation of cancer cells when NOTCH1 was knocked down." (PMID 35205828, 2022). "Overexpression of TGF-β increases the levels of GLS1 in HCC and in T-cell acute lymphoblastic leukaemia (T-ALL), increased glutaminolysis induces NOTCH1 signaling, promoting growth and survival of cancer cells." (PMID 36618350, 2022). "Although the NOTCH1 pathway is not fully understood, it is common sense that the NOTCH1 pathway is involved in the development of various cancers." (PMID 35897085, 2022). "On the contrary, the inhibition of Notch1 reversed the mesenchymal phenotype of cancer cells to the epithelial one and increased the sensitivity of cancer cells to gefitinib." (PMID 35954450, 2022). "Another study found that vaspin reduced cancer cell motility and proliferation by blocking the NF-B/Notch1 signaling pathway." (PMID 36072980, 2022). "Quercetin and ionizing radiation combination therapy exhibits anti-cancer effects by targeting CSCs and inhibiting Notch1 signaling." (PMID 36158694, 2022). "Although studies regarding miR-363 levels in pediatric ALL are lacking, network analysis was recently used to decipher the interplay between this miRNA and NOTCH1 as a pathogenetic marker for cancer development." (PMID 36010971, 2022). "Our aim was to investigate the effectiveness of Crenigacestat, a selective inhibitor of NOTCH1 signaling, against the cross-talk between cancer cells and the surrounding ecosystem in an in vivo HuCCT1-xenograft model." (PMID 35457006, 2022). "Considering Notch1 can contribute in cancer development, we validated that tRF-21-RKP4P9L0 can modify LUAD by influencing proliferation, migration and invasion." (PMID 35115004, 2022). "Our findings indicate that the Cbl-b-Notch1 axis is a novel promising target for cancer immunotherapy." (PMID 36090975, 2022). "Increased expression of Notch1, Notch3 or Notch4 is able to induce breast epithelial cell transformation into cancer cells." (PMID 35682974, 2022). "A recent study showed that downregulating the HIF-1α/NOTCH-1 pathway was able to eliminate CD44+ cancer stem-like cell phenotypes to enhance the malignancy and chemo-resistance in neck squamous cell carcinomas." (PMID 36358852, 2022). "Dll4 is expressed in cancer cells and activates Notch1 signaling in an autocrine manner, while Jag1 is expressed in the neighboring HSCs and activates Notch2 signaling in adjacent cancer cells." (PMID 35064244, 2022). "Notch1 has been investigated to have roles in cancer cell proliferation, migration and invasion, we then explored these functional impacts of tRF-21-RK9P4P9L0 in LUAD cell lines." (PMID 35115004, 2022). "Contrarily, some miRNAs inhibit cancer development such as miR-195-5P and miR-34 by inhibiting the Notch1 pathway, miR-99a through inhibiting the Mtor pathway, miR-519d and miR-128 by activating caspases and inducing apoptosis." (PMID 35327559, 2022). "Our work provides evidence that targeting the Cbl-b-Notch1 axis is a novel promising strategy for cancer immunotherapy." (PMID 36090975, 2022). "Specifically, we described a new pathway that is amenable to pharmacological targeting and has promising selectivity for Notch1 in T-cells versus cancer cells, a feature that is very important for Notch-targeted therapies." (PMID 36090975, 2022). "The anticarcinogenic emodin inhibits cancer cells growth, increases the mRNA and protein expression of Notch1 while significantly decreasing the mRNA and protein expression levels of VEGF." (PMID 35208583, 2022). "WT mouse CRIPSCs also had higher expression of the genes related to stem cells (Psca, Atg9b, Sox2, Sox9), cell cycle (Cdk6), mammary luminal progenitor cells (Notch3 and Notch1), and cancers." (PMID 35841025, 2022).
cancer (continued). "Vaspin inhibits cancer cell proliferation and chemotaxis by inhibiting NF-κB/Notch1 signaling pathway." (PMID 36072980, 2022). "It is known that, in many types of cancers including breast, multiple receptor Tyrosine Kinases stimulate Ras signaling, and Ras overexpression/activation induces upregulation of Notch1." (PMID 35682974, 2022). "It deubiquitinate Notch 1, increasing Notch1-dependent c-Myc expression and promoting cancer progression by reducing cell cycle arrest and apoptosis." (PMID 35884607, 2022). "Downregulation of cancer stem cell markers octamer-binding transcription factor 4 (oct4), Notch1 (Neurogenic locus notch homolog protein 1), epithelial cellular adhesion molecule (EpCAM), and CD44 was observed in the stem cells embedded in mammosphere culture." (PMID 36362950, 2022). "In this study, we conducted a database search and found that two other tumor suppressor genes, NOTCH1 and FAT1, have a high nonsense mutation rate (NOTCH1: 19.62% and FAT1: 40.11%) in HNSCC mutation samples in the COSMIC database compared to other cancers." (PMID 36428516, 2022). "We showed that promoting Notch1 signaling by blocking Cbl-b-mediated degradation results in a robust increase in anti-cancer T-cell responses and resistance to immunosuppression." (PMID 36090975, 2022). "In FAS knockout cells, restoring the NOTCH1 intracellular domain stimulated cancer spheroid formation." (PMID 35249111, 2022). "NOTCH-1 stimulates cancer development at an early stage of cervical cancer, while it represses cancer growth at a later stage." (PMID 36359888, 2022). "To validate HIF-1α as a therapeutic target for a small cell population or an early stage of cancer progression prior to the creation of a hypoxic core, we established in vivo models using a doxycycline-inducible sh-Notch1 U251-MG cell line and chetomin." (PMID 36183290, 2022). "The genomic profiling of GC PNM also identified alterations in other cancer-related genes, including NOTCH1, NOTCH2, NF1, and STK11." (PMID 35515115, 2022). "Actually, current results showed that NLE1 presented similar functions with Notch1 in the regulation of human cancer." (PMID 36818671, 2022). "In particular, cancer cells several rows behind the leading edge exhibited upregulated Notch1, Nrf2, and miR-200c while cells at the leading edge expressed ZEB1, Dll4, and Jagged1." (PMID 35480877, 2022). "HIF-2α increases the expression of DLL4 at the transcriptional level by binding directly to site 3 of the DLL4 promoter region, which then activates Notch1 signals, causing downstream secretion of MMP-9 for increased cancer cell migration." (PMID 35385679, 2022). "We found significant differences in mutation frequencies of NOTCH1 and NOTCH2, copy number variations (CNVs) at both gene and chromosomal arm levels, and cancer-related HIPPO, WNT, and NRF2 signaling pathways between ESCC tumors and normal mucosa." (PMID 35515115, 2022). "Previous studies by our group showed Msi-1 to be overexpressed in EC, especially in cancer stem cells (CSC) and also linked Msi-1 to Notch-1 expression." (PMID 35619161, 2022). "Our group and others have found that activation of the Notch1 pathway contributes to cancer cell proliferation, invasion, and migration and drug resistance in tumors." (PMID 36212390, 2022). "The complex interplays between Nrf2, EMT, and Notch1 and their roles in collective cancer migration remain poorly understood." (PMID 35480877, 2022). "NOTCH1 controls the genes involved in early differentiation, having different phenotypic consequences depending on the genetic background of the cancer, including the acquisition of properties like those of progenitor cells." (PMID 35739348, 2022). "In vitro and in patient database analyses, we demonstrate that low Msi-1 is linked to a decrease in Notch-1, DNA-PKcs and TERT, all related to cancer stem cells and therapy resistance, and an increase in p21, an anti-proliferative marker." (PMID 35619161, 2022).